HCK (HCK proto-oncogene, Src family tyrosine kinase)
Diseases named in the same sentence as HCK in open-access papers (continued):
Sharing a sentence is not in itself a finding about the gene and the disease.
breast carcinoma (continued). "First, to understand the role of HCK expression in the metastasis of breast cancer patients, the expression of HCK was detected by immunohistochemistry in 30 pairs of primary and metastatic breast cancer specimens." (PMID 33162805, 2020). "Using clinical breast cancer specimens, we found that HCK expression was related to a larger tumor size, a greater number of PALNs, distant metastasis, and even death." (PMID 33162805, 2020). "In this research, we found that HCK expression negatively influence the prognosis of breast cancer patients, and explored the regulation mechanism of HCK in cancer and even in other related disease." (PMID 33162805, 2020). "Both TAOK2 and HCK are overexpressed in breast cancers, based on patient data provided by cBioPortal." (PMID 28771473, 2017). "Overall, most in vitro and in vivo animal experiments showed findings consistent to our study, that is, HCK negatively impacts survival outcomes and thus may as a potential therapeutic target for breast cancer treatment." (PMID 33162805, 2020). "Ultimately, HCK is an adverse independent predictor of survival outcomes in breast cancer and may serve as a potential therapeutic target for breast cancer patients." (PMID 33162805, 2020). "Collectively, these findings support that HCK is an adverse prognosis factor of breast cancer." (PMID 33162805, 2020). "All the findings proved that HCK promoter methylation may contribute to the development of breast cancer." (PMID 33162805, 2020). "The role of HCK expression in the prognosis of breast cancer patients is unclear." (PMID 33162805, 2020). "In addition, we also explored the level of HCK mRNA expression in breast cancer using UALCAN dataset." (PMID 33162805, 2020). "While the research may be the first research to evaluate the clinical implications of HCK expression in breast cancer patients, it also has some limitations." (PMID 33162805, 2020). "Thus, this research aimed to explore the effect of HCK expression in the survival outcomes of breast cancer patients." (PMID 33162805, 2020). "Overall, HCK may be an oncogene in the development of breast cancer and thus may as a novel biomarker and therapeutic target for breast cancer." (PMID 33162805, 2020). "The expression of HCK was highest in C6 immune subtype of breast cancer." (PMID 33162805, 2020). "However, the role of HCK expression in the survival outcome of cancer patients, particularly those with breast cancer, remains unclear." (PMID 33162805, 2020). "Thus, future studies should aim to focus on biochemical experiments that could explain the mechanisms by HCK expression can affect the development of breast cancer and determine the feasibility of HCK-targeted drugs in breast cancer treatment." (PMID 33162805, 2020). "In addition, we also found that HCK may affect progression of breast cancer by some immune-related biological pathways and processes." (PMID 33162805, 2020). "However, very few studies reported the clinical implications of HCK expression in breast cancer." (PMID 33162805, 2020). "Thus, this study aimed to explore the clinical implications of HCK expression in breast cancer." (PMID 33162805, 2020). "This was supported by the micromolar/submicromolar affinity of quercetin towards proto-oncogene serine/threonine–protein kinase (PIM-1) and hematopoietic cell kinase (HCK), both involved in breast cancer." (PMID 33946222, 2021). "Furthermore, HCK overexpression may be caused by suppression of C-terminal Src kinase and Cbp/PAG regulation pathway, such as in hepatocellular carcinoma 44, and by tyrosine phosphatases, such as in breast cancer." (PMID 33162805, 2020). "Among these 40 breast cancer patients, the level of HCK was higher in 6 triple-negative breast cancer patients than in 27 luminal type and 7 HER2 positive breast cancer patients." (PMID 33162805, 2020). "In TCGA data provided by the Cancer Genome Atlas, we find HCK, LYN, LCK, and CSK are higher in basal-like breast cancer subtypes." (PMID 28771473, 2017).
breast carcinoma (continued). "We show relative expressions of TAOK2, HCK and STK10 in different breast cancer cell lines in S6 Fig." (PMID 28771473, 2017). "Then, immunochemistry was used to analyze HCK expression in breast cancer specimens, non-cancer tissues and metastatic cancer tissues." (PMID 33162805, 2020). "In different race of breast cancer patients, Caucasian patients had highest HCK mRNA expression, Asian patients had lowest HCK mRNA expression; the difference was also not significant." (PMID 33162805, 2020). "IHC of HCK expression in 20 breast cancer tissues and 20 breast non-cancer tissues collected in our hospital also showed that HCK expression was significantly higher in cancer tissues than that in non-cancer tissues (P=0.025)." (PMID 33162805, 2020). "Oncomine analysis revealed that the level of HCK mRNA transcripts was significantly higher in breast cancer than in non-cancer samples." (PMID 33162805, 2020). "We found that the level of HCK mRNA transcripts and HCK protein expression were both higher in highly invasive and metastatic BT549 and MDA-MB-231 triple-negative breast cancer cells than that in less invasive and metastatic SKBR3 and MCF7 breast cancer cells." (PMID 33162805, 2020). "Among ER+ breast cancers, 15% harbored FGFR1 gene amplification and/or mRNA overexpression whereas 2.5, 1.9, 2.4, and 1.7% harbored amplification and/or mRNA overexpression of CRKL, HCK, FRK, and FGR, respectively." (PMID 30914635, 2019). "We found that breast cancer tissues have more HCK mRNA transcripts than non-cancer tissues." (PMID 33162805, 2020). "Second, we only explore the regulatory pathway of HCK based on bioinformation tools and did not validate the molecular mechanisms using in vitro cell experiments and in vivo animal experiments to explain the biological function of HCK expression in breast cancer." (PMID 33162805, 2020). "Additionally, HCK expression was higher in highly invasive and metastasis MDA-MB-231 cell lines than in less invasive and metastasis SKBR3 and MCF7 cell lines, indicating that HCK may be related to invasion and metastasis in breast cancer." (PMID 33162805, 2020). "Furthermore, members of the SFK family, including HCK, have been investigated as regulators of cell migration and motility in cancers, although the specific role of HCK in acquisition of a motile phenotype in metastatic breast cancers has not yet been investigated." (PMID 28771473, 2017). "Two of these candidate kinases, TAOK2 and HCK, have not been previously investigated as regulators of EMT and acquisition of cell motility/invasion in breast cancer, although one group recently referenced TAOK2 as a potential activator of TNBC cell growth." (PMID 28771473, 2017).
colon cancer (8 papers, 2015 to 2025). "The change of myeloid-related HCK expression owing to STAT3 activation can regulate cancer-associated macrophage polarization and the growth of colon cancer." (PMID 33162805, 2020). "HCK has previously been identified and studied as a promising therapeutic target for colon cancer where HCK acts to promote tumor progression." (PMID 33233470, 2020). "Elevated HCK activity is also observed in many solid malignancies, including breast and colon cancer, and correlates with decreased patient survival rates." (PMID 26087188, 2015). "Inhibition of HCK activity suppresses myeloid cell-mediated colon cancer progression." (PMID 35884544, 2022). "As a consequence, TAMs and granulocytes release mediators such as arginase 1 (ARG1) and hematopoietic cell kinase (HCK) that impair T-cell responses and promote tumor invasion in lung and in colon cancers." (PMID 34084172, 2021). "Pharmacological inhibition or genetic reduction of HCK activity suppressed M2-like TAM activation and the growth of colon cancer xenografts, making HCK a promising target for cancer therapy." (PMID 30349530, 2018).
acute myeloid leukemia (7 papers, 2015 to 2025). Acute myeloid leukemia (AML) is a group of neoplasms arising from precursor cells committed to the myeloid cell-line differentiation. "Previous studies had suggested that expression of FGR and HCK in acute myeloid leukemia blasts was associated with early commitment and differentiation events in the monocytic and granulocytic lineages." (PMID 32708273, 2020). "However, decreased HCK activation has also been reported in a small number of acute myeloid leukemia and acute promyelocytic leukemia patients." (PMID 26087188, 2015). "Thus, HCK inhibition could represent a novel approach for the treatment of the acute myeloid leukemia." (PMID 33842460, 2021). "HCK is involved in immune and inflammatory responses and has been implicated in various leukocyte-related disorders, particularly chronic myelogenous leukemia (CML) and acute myeloid leukemia (AML)." (PMID 41415030, 2025). "Bioinformatic analysis showed that HCK mRNA co-occurred with NLRP12 mRNA, but not with other NLRP mRNAs, in blood and marrow samples from acute myeloid leukemia (AML) patients." (PMID 32226298, 2020).
colorectal cancer (7 papers, 2015 to 2025). A primary or metastatic malignant neoplasm that affects the colon or rectum. "Upregulation of HCK in mice accelerates the progression of endogenous colonic malignancies and promotes human colorectal cancer xenograft progression." (PMID 34363435, 2021). "Downregulation of HCK increases the proliferation of colorectal cancer cells via the transcription activator‐6‐dependent Th2 cytokine signalling pathway." (PMID 34363435, 2021). "In colorectal cancer, HCK is involved in decreased proliferation and poorer differentiation, suggesting HCK overexpression promotes tumorigenesis." (PMID 32484210, 2020). "Likewise, in mice excessive HCK activity promotes the growth of endogenous colonic malignancies and of human colorectal cancer cell xenografts." (PMID 32484210, 2020). "Importantly, in the organoid culture system, BMX and HCK upregulations resulted in the formation of multilayered polyp-like buds protruding towards the organoid lumen, mimicking the pathological polyp morphology often observed in colorectal cancer." (PMID 35221332, 2022).
lymphoma (6 papers, 2011 to 2024). A malignant (clonal) proliferation of B- lymphocytes or T- lymphocytes which involves the lymph nodes, bone marrow and/or extranodal sites. "SYK can also be activated by the hematopoietic cell kinase (HCK) in MyD88-mutated lymphoma cells, and, at the same time, HCK can be triggered either by mutated MyD88 directly or through IL-6." (PMID 35628381, 2022). "For example, PAX5 activates HCK transcription by inducing active chromatin in the HCK promoter in MYD88-mutated lymphoma cells." (PMID 36387144, 2022). "Abnormal expression of HCK plays a key role in the proliferation and survival of mantle cell lymphoma and the retention of malignant cells in the lymphatic microenvironment supporting growth and survival, thus promoting the occurrence of lymphoma." (PMID 35185791, 2022). "Compared to the lymphoma group, the protein quantitative analysis of the LGBLEL group exhibited significantly differentially expressed CCL28, CCR1, CXCL17, HCK, GNB5, NRAS, and VAV2 (p = 0.003, 0.011, 0.001, 0.024, 0.005, 0.019, and 0.031, respectively)." (PMID 39451532, 2024). "WB revealed that, compared to the lymphoma group, the LGBLEL group exhibited significantly higher expression of CCL28, CXCL17, HCK, GNB5, NRAS, and VAV2 (p = 0.012, 0.005, 0.009, 0.011, 0.008, and 0.003, respectively) and lower expression of CCR1 (p = 0.014)." (PMID 39451532, 2024). "In this study, key genes from the chemokine signaling pathway—HCK, GNB5, NRAS, and VAV2—were validated, confirming their differential expression between LGBLEL and lymphoma and suggesting their important role in the malignant transformation of LGBLEL." (PMID 39451532, 2024). "Compared to the lymphoma group, the LGBLEL group exhibited higher expression levels of CCL28, CXCL17, HCK, GNB5, NRAS, and VAV2 (p = 0.001, <0.001, <0.001, <0.001, 0.020, and <0.001, respectively) and lower expression of CCR1 (p = 0.002)." (PMID 39451532, 2024). "RT-qPCR showed that, compared to the lymphoma group, the LGBLEL group had significantly higher expression of CCL28, CXCL17, HCK, GNB5, NRAS, and VAV2 (p = 0.001, <0.001, <0.001, <0.001, =0.020, <0.001, respectively) and lower expression of CCR1 (p = 0.002)." (PMID 39451532, 2024). "Compared to the lymphoma group, the LGBLEL group showed higher expression of CCL28, CXCL17, HCK, GNB5, NRAS, and VAV2 (p = 0.012, 0.005, 0.009, 0.011, 0.008, and 0.003, respectively) and lower expression of CCR1 (p = 0.014)." (PMID 39451532, 2024).
renal fibrosis (6 papers, 2020 to 2025). A final common manifestation of a wide variety of chronic kidney diseases characterized by glomerulosclerosis and tubulointerstitial fibrosis. "HCK has been implicated in the pathogenesis of renal fibrosis, a common outcome in IgAN, and is known to modulate macrophage functions such as inflammatory polarization and migration." (PMID 39777260, 2024). "The HCK function has been shown to promote renal fibrosis through increasing macrophage proliferation and migration." (PMID 40022609, 2025). "We then confirmed the role of macrophage HCK in renal fibrosis by using macrophage specific HCK knockout mice in renal fibrosis models, with consistent reduced macrophage infiltration in the diseased kidney." (PMID 37463911, 2023). "The previous study revealed that HCK is an important Src kinase family member that participated in the progression of renal fibrosis." (PMID 36568106, 2022). "Renal fibrosis is a common sequela of chronic renal allograft injury and recent work identifies HCK as an important driver of this fibrosis, with HCK overexpression activating fibrotic pathways, and HCK knockdown inhibiting fibrotic pathways." (PMID 33233470, 2020). "Recent findings suggest that HCK contributes to renal fibrosis by regulating macrophage activity." (PMID 39777260, 2024). "The current study elucidates mechanisms downstream of HCK regulating macrophage activation and polarization via autophagy in CKD and identifies that selective HCK inhibitors could be potentially developed as a new therapy for renal fibrosis." (PMID 37463911, 2023). "Since single cell RNA sequencing (scRNA-seq) analysis suggests that HCK expresses mostly in pro-inflammatory infiltrating macrophages in the kidney, we studied here the role and the mechanisms of HCK in regulation of macrophage function in the context of renal fibrosis." (PMID 37463911, 2023). "However, how HCK contributes to renal fibrosis remains unclear." (PMID 37463911, 2023). "We also developed a non-toxic specific HCK inhibitor ie a target-to-hit compound BT424, and demonstrated its regulation of macrophage function leading to attenuation of progressive renal fibrosis." (PMID 37463911, 2023).
atherosclerosis (5 papers, 2020 to 2024). A disease characterized by the build-up of fatty material and calcium deposition in the arterial wall resulting in partial or complete occlusion of the arterial lumen. "LCP2, EIF4EBP1, HCK, and PPP4C were demonstrated to be highly expressed, and SYNJ2 was demonstrated to be lowly expressed in atherosclerosis compared to the control group, which can be diagnostic biomarkers for patients with atherosclerosis." (PMID 35845072, 2022). "However, the specific mechanism of HCK in atherosclerosis development still need further elaboration." (PMID 33519905, 2020). "LCP2, EIF4EBP1, HCK, and PPP4C were demonstrated to be highly expressed and SYNJ2 was demonstrated to be lowly expressed in the atherosclerosis mice model." (PMID 35845072, 2022). "“HCK proto-oncogene, Src family tyrosine kinase” (HCK) was identified as a hub gene using weighted correlation network analysis (WGCNA) and validated for the predictive value in identifying future MI-induced heart failure (HF) and in atherosclerosis plaque progression." (PMID 35845072, 2022). "RBM47, HCK, CD53, TYROBP, and HAVCR2 were identified as common hub genes, which were validated to be upregulated in advanced atherosclerotic plaques, to well distinguish CAD patients from non-CAD people and to regulate immune cell function-related mechanisms in advanced atherosclerosis." (PMID 33519905, 2020).
chronic myeloid leukemia (5 papers, 2015 to 2022). "However, other studies found that in increased HCK expression in chronic myeloid leukemia (CML) and renal cancer is associated with an increased survival time 42,37." (PMID 33162805, 2020). "In chronic myeloid leukemia, BCR-ABL1 activates several pro-survival substrates, including HCK, supporting a role for HCK in BCR-ABL1-induced proliferation and survival." (PMID 31065022, 2019).
acute lymphocytic leukemia (4 papers, 2015 to 2025). "Our study gives a comprehensive analysis, involving the common gene signatures of HCK, NOG, and RNF125 in pediatric acute lymphoblastic leukaemia and pediatric sepsis, together with related biological mechanism." (PMID 38123749, 2025).
multiple myeloma (4 papers, 2015 to 2023). "As in multiple myeloma cells, we also found that HCK directly associates with GP130 in embryonic stem cells." (PMID 26087188, 2015). "Together, these results implicate HCK, and possibly its association with the GAB adaptor proteins, as key players in GP130-mediated multiple myeloma pathogenesis." (PMID 26087188, 2015). "In line with this, expression of a kinase-dead HCK mutant in mouse myeloma 7TD1 cells elicited a dominant-negative effect on cell proliferation, thereby providing additional evidence that HCK is required to transmit GP130-dependent growth signals." (PMID 26087188, 2015). "The mechanism by which the GP130/HCK-containing complex promotes IL6-induced activation of ERK and PI3K in multiple myeloma cells is dependent on the adaptor proteins GAB1 and GAB2, which are constitutively associated with HCK." (PMID 26087188, 2015). "Similarly, hematopoietic cell kinase (HCK) has been reported to induce GAB1 phosphorylation in response to IL-6 in multiple myeloma cells." (PMID 37627207, 2023). "HCK-mediated phosphorylation of GAB1 induces proliferation and survival in IL-6-induced multiple myeloma cells." (PMID 37627207, 2023). "In multiple myeloma cells, various investigators have identified FYN, HCK and LYN in co-immunoprecipitates with GP130, and stimulation of these cells with IL6 results in increased activation of these SFKs." (PMID 26087188, 2015). "Importantly, kinase-dead HCK mutants, or treatment with the SFK inhibitor PP2, reduced IL6-induced tyrosine phosphorylation of intracellular signaling proteins and significantly decreased myeloma cell survival and proliferation." (PMID 26087188, 2015).
Waldenstrom macroglobulinemia (4 papers, 2020 to 2024). "HCK is overexpressed in Waldenstrom macroglobulinemia (WM) and other hematological malignancies and is targeted by Ibrutinib for the induction of apoptosis in chronic lymphocytic leukemia." (PMID 33488754, 2020). "Recently, KIN-8194, a dual inhibitor of BTK (IC50 = 0.915 nM) and HCK (IC50 < 0.495 nM), was shown to potently affect the survival of ABC-type DLBCL and Waldenström Macroglobulinemia with a pathogenic Myd88-L265P mutation, while minimally affecting healthy B-cells." (PMID 38454120, 2024). "The hematopoietic cell kinase (HCK) regulates BTK activation and represents a potential therapeutic target in Waldenstrom macroglobulinemia (WM)." (PMID 36051045, 2022). "A Bruton tyrosine kinase (BTK) inhibitor and hematopoietic cell kinase (HCK) inhibitor are used in the treatment of chronic lymphocytic leukemia, mantle cell lymphoma, and Waldenstrom’s macroglobulinemia." (PMID 33912588, 2021).